DOCK8 (dedicator of cytokinesis 8)
Diseases named in the same sentence as DOCK8 in open-access papers (continued):
Sharing a sentence is not in itself a finding about the gene and the disease.
hyper-IgE syndrome (24 papers, 2012 to 2025). A condition that is characterized by elevated serum IgE, dermatitis, and respiratory infections. "Initially recognized as the AR-HIES the autosomal recessive form of hyper-IgE syndrome, is caused by gene mutations in the DOCK8 gene." (PMID 40317072, 2025). "Patient 34 had two DOCK8 variants (p.V1027I and p.D1347E), and a very convincing clinical phenotype for hyper IgE syndrome." (PMID 28750028, 2017). "In DOCK8-deficient hyper IgE syndrome the high mortality and deaths in early age seem to justify allogenic hematopoietic stem cell transplantation." (PMID 26060590, 2015). "Interestingly, findings linking IL-31 expression with patients suffering from Dedicator of cytokinesis protein 8 (DOCK8) deficiency-related hyper IgE syndrome pointed to an important upstream regulation pathway." (PMID 33644104, 2021). "Hyper-IgE syndrome (HIES), a disease caused by STAT3 loss of function (LOF) and DOCK8 deficiency, is the classic example of an IEI that is frequently addressed to allergy units." (PMID 35757131, 2022). "Similarly, the development of intracellular staining protocols to detect expression of SAP, XIAP, or DOCK8 expedites the rapid diagnosis of the X-linked lymphoproliferative diseases or an autosomal recessive form of hyper-IgE syndrome (HIES), respectively." (PMID 31552044, 2019). "Twelve patients with suspicion of Hyper-IgE syndrome were examined for molecular defects—4 were found to have pathogenic variants (1 in DOCK8, 3 in STAT3); 7 had no variants." (PMID 35729272, 2022). "DOCK8 (hyper IgE syndrome) was expressed in antigen presenting and T cells." (PMID 32727470, 2020). "Deletion of the dedicator of cytokinesis 8 (DOCK8) gene is considered to be the autosomal recessive form of hyperimmunoglobulin E syndrome which is a rare type of primary immunodeficiency disease characterized by elevated levels of IgE antibody, eczema, and recurrent staphylococcal infections." (PMID 27113444, 2016). "These symptoms are a hallmark of Hyper-IgE Syndromes (HIES), particularly those caused by STAT3 and DOCK8 deficiencies." (PMID 41035657, 2025). "The immunological mechanisms underlying autosomal recessive (AR) hyper-IgE syndrome (AR-HIES) caused by DOCK8 mutations remain unclear, leading to a lack of specific therapeutic options." (PMID 39616183, 2024).
primary immunodeficiency (24 papers, 2016 to 2026). "Similar modifier gene effects have been described in other primary immunodeficiencies, such as DOCK8 deficiency and STAT1 GOF mutations, where additional genetic variants contribute to phenotypic variability and disease severity." (PMID 40951253, 2025). "Dedicator of cytokinesis 8 (DOCK8) deficiency is a primary immunodeficiency disease caused by mutations in exon 45 of the DOCK8 gene." (PMID 39329018, 2024). "The diagnoses of the patients included primary immunodeficiency diseases (DOCK8: n=4, STAT3: n=1, GATA2 mutations: n=11), lymphoma (n=3), leukemia (n=5), and sickle cell disease (n=5)." (PMID 38756303, 2024). "Dedicator of cytokinesis 8 (DOCK8) deficiency represents a primary immunodeficiency with a wide range of clinical symptoms, including recurrent infections, atopy, and increased malignancy risk." (PMID 39044832, 2024). "DOCK8 deficiency is a primary immunodeficiency characterized by recurrent infections, severe allergic disease, and autoimmunity." (PMID 33787566, 2021). "Both Wiskott-Aldrich syndrome (WAS) and dedicator of cytokinesis 8 (DOCK8) deficiency are primary immunodeficiency diseases caused by mutations in genes that result in defective organization of the cytoskeleton in hematopoietic tissues." (PMID 31750279, 2019). "Human DOCK8 mutations cause primary immunodeficiencies associated with perturbed migration, altered function of myeloid and NK cells." (PMID 29030607, 2017). "DOCK8 mutations cause primary immunodeficiencies that clinically manifest as severe allergy, skin and lung infections in humans." (PMID 29030607, 2017). "DOCK8 deficiency is a primary immunodeficiency, currently known as Inborn Errors of Immunity (IEI) affecting both cellular and humoral immunity, thus leading to various clinical presentations ranging from infections, autoimmunity, inflammations and malignancies." (PMID 42090074, 2026). "Loss-of-function mutations in the DOCK8 gene cause a rare form of primary immunodeficiency." (PMID 27113444, 2016). "In addition to its observed benefit in patients with subtle NK cell dysfunction, IFN-α-2b demonstrated marked clinical efficacy in a patient with Dedicator of Cytokinesis 8 (DOCK8) deficiency, a primary immunodeficiency associated with severe, recalcitrant cutaneous warts." (PMID 40565110, 2025). "Primary immunodeficiency, such as is associated with EVER1, EVER2, GATA2, CXCR4, and DOCK8 mutations, as well as combined immunodeficiency, such as in bare lymphocyte syndrome, is associated with extensive HPV infection." (PMID 38637854, 2024). "As with a few other primary immunodeficiencies, there have been reported cases of somatic reversion leading to partial re-expression of DOCK8 protein in some cell linages." (PMID 35373187, 2022). "Targeted genetic testing with the Invitae primary immunodeficiency panel revealed two heterozygous VUS, that is, in DOCK8 (C.277G>T, p.Val93Leu) and FOXN1 (c.1205del, p.Pro402Leufs*148)." (PMID 39008056, 2024). "We report a novel primary immunodeficiency, and a differential molecular diagnosis to CXCR4‐,DOCK8‐,GATA2‐,MAGT1‐,MCM4‐,STK4‐,RHOH‐,TMC6‐, and TMC8‐related diseases." (PMID 27896283, 2016).
viral infections (23 papers, 2012 to 2025). "This was tested in our current study by the identification of homozygous variants in IFNAR1 and DOCK8 in a young individual presenting with a history of severe and recurrent viral infections." (PMID 39098944, 2024). "Individuals with DOCK8 mutations exhibit recurrent sinopulmonary infections specific for humoral immunodeficiency and severe viral infections suggestive of T-cell dysfunctions." (PMID 35386989, 2021). "We have found that patients with DOCK8 deficiency are particularly predisposed to mucocutaneous viral infections like molluscum contagiosum and HSV infections." (PMID 31191561, 2019). "Mutations or deletions of Dock8 lead to a form of T and B cell immunodeficiency characterized by recurrent viral infections, greater susceptibility to cancer, and elevated serum levels of IgE." (PMID 24996924, 2014). "Patients with autosomal recessive hyper IgE syndrome lack the connective tissue and skeletal manifestations, but an increased rate of viral infections (DOCK8 mutations) and intracellular bacteria (TYK2 mutations)." (PMID 25379309, 2014). "Despite this phenotype, DOCK8 deficient mice mount a relatively normal primary immune response to viral infection in vivo, but show significantly impaired persistence and survival of memory CD8+ T-cells." (PMID 22461835, 2012). "Upon virus infection, DOCK8 mutation CD4+ T cells have a Th2 effector fate." (PMID 39329018, 2024). "Viral infections are frequently observed in DOCK8‐deficient patients." (PMID 39329018, 2024). "The relation of DOCK8 with AD has only been sparsely reported thus far, whereas DOCK8 deficiency due to recessive damaging variants is a well-documented cause of hyper IgE syndrome and a tendency to viral infections." (PMID 37533579, 2023). "Interestingly, DOCK8 deficiency in humans due to bi-allelic mutations results in combined immunodeficiency characterized by recurrent viral infections and early-onset malignancy." (PMID 37108808, 2023). "This defect due to bi-allelic mutations in DOCK8 gene is characterized by distinctive clinical features including severe viral infections, neurological complications, increased risk of malignancies, autoimmunity in addition to the clinical triad observed in STAT3 deficiency." (PMID 36703986, 2022). "The characteristic features associated with DOCK8 deficiency include elevated IgE levels, recurrent bacterial and viral infections, atopic dermatitis, mucocutaneous candidiasis, asthma, severe food and environmental antigens allergies, and an increased incidence of malignancy." (PMID 35386989, 2021). "The importance of pDCs and NK cells in controlling virus infections is illustrated by the primary immunodeficiency disorders, such as DOCK8 deficiency and primary NK cell deficiency, in which deficiency of these cells is associated with an increased susceptibility to multiple virus infections." (PMID 28725225, 2017). "Interestingly, loss-of-function mutations in DOCK8 were recently identified in patients with severe combined immunodeficiency, characterized by repeated bacterial and viral infections." (PMID 22461835, 2012). "DOCK8 deficiency was suspected in patients with HIES clinical phenotype and severe viral infection, food allergies, and/or low IgM levels." (PMID 36703986, 2022). "There is the observation that AR-HIES can be caused by mutations in the dedicator of cytokinesis 8 (DOCK8) gene, which results in both increased susceptibility to recurrent viral infections and CMC." (PMID 26845151, 2016). "Consequently, most of patient II.2′s T cells were able to produce wildtype DOCK8 transcripts likely leading to a survival advantage and clonal expansion of DOCK8 expressing T cells under selective pressure, e.g. exerted by viral infections, as reported for DOCK8-HIES and other PIDs32,34,35." (PMID 30425284, 2018).
viral infections (continued). "In addition, clinical phenotype of DOCK8 deficiency may be significantly variable including for the same mutation with features, which may not include the typical viral infections and the food allergy." (PMID 36703986, 2022). "Other Genetic Forms of HIES/Combined Immunodeficiency (CID): Although conditions like DOCK8 deficiency (now classified as CID) can present with high IgE and eczema, our patient's history was dominated by bacterial and fungal infections without severe viral infections, aligning more with STAT3-HIES." (PMID 41458089, 2025).
eczema (22 papers, 2014 to 2025). "Dysfunction of regulatory T-cells together with S. aureus exposure have been suggested to drive severe eczema in DOCK8 deficiency and DOCK8-deficient murine neutrophils were prone to undergo S. aureus-induced cell death." (PMID 38720948, 2024). "Individuals with DOCK8-deficiency have a high incidence of allergic diseases and eczema, hyper IgE, eosinophilia, and a profound type-2 CD4+ T helper cell (Th2) bias, leading to IL-6 overexpression." (PMID 39044832, 2024). "In patients with severe allergic phenomena (eczema, eosinophilia, food allergies) measuring IgE levels can also be helpful in identifying certain disorders, i.e., Hyper IgE syndromes such as DOCK8 deficiency, STAT3-HIES and PGM3 deficiency." (PMID 35371103, 2022). "The other patient (HIES02) additionally had a homozygous frameshift mutation of DOCK8 and thus had presented with recurrent pneumonias, severe sinusitis, and eczema with recurrent skin infections and diarrhea." (PMID 34390440, 2021). "Pediatricians in areas with a high prevalence of consanguinity marriage should have a high index of suspicion of DOCK8 deficiency in patients with recalcitrant eczema, and frequent respiratory and skin infectious episodes." (PMID 31242861, 2019). "With her symptoms of eczema and IgE elevation, along with her brother's history of recurrent sinopulmonary infections and warts, targeted sequencing of DOCK8 was performed revealing compound heterozygous mutations for the two siblings." (PMID 28293550, 2017). "Highly elevated serum IgE levels, atopic manifestations such as severe eczema and allergies, and failure to thrive distinguish DOCK8 deficiency and WAS from MST1 deficiency." (PMID 26801501, 2016). "DOCK8 deficiency results in autosomal recessive hyper-IgE syndrome with severe allergic manifestations, characterized by severe eczema, recurrent skin infection, mucocutaneous candidiasis, elevated serum IgE levels, and eosinophilia." (PMID 24497979, 2014). "Comparable to almost all earlier observations, we recognized a greater frequency of eczema/atopic dermatitis in CID patients due to the consistent presence of eczema in hyper IgE syndrome and DOCK8 deficiency, that is, one of the main gene defects in our patients with cutaneous manifestations." (PMID 37237458, 2023). "Moreover, CARMIL2 interactome include DOCK8, that is mutated in patients presenting with autoimmune disorders, eczema and compromised Treg function." (PMID 33723309, 2021). "DOCK8-deficient patients present early in life with eczema, viral cutaneous infections, chronic mucocutaneous candidiasis, bacterial pneumonia, and abscesses, together with eosinophilia, thrombocytosis, lymphopenia, and variable dysgammaglobulinemia that usually includes Hyper-IgE." (PMID 34195158, 2021). "On the other hand, the majority of patients with DOCK8 and STAT3-AD (LOF) mutations developed eczema, dermatitis, and viral skin infections." (PMID 37237458, 2023). "Eczema is also a common manifestation of T-cell disorders, including Wiskott Aldrich Syndrome (WAS), autosomal dominant STAT3 deficient Hyper IgE syndrome (STAT3-HIES) and DOCK8 deficiency." (PMID 35371103, 2022). "This panel should include the ten HIES genes, DOCK8 gene, TYK2 gene, genes that could be responsible for atypical clinical presentations, and genes associated with moderate to severe refractory eczema and elevated Immunoglobulin E." (PMID 36703986, 2022). "However, comparable to our earlier observations and those reported from elsewhere, eczema is a consistent feature of HIGE syndrome and WAS and a predominant feature in patients with CID including DOCK8, RAG1, and MHC II deficiency." (PMID 34659256, 2021). "Eczema and eczematoid rashes were more often seen in patients with CID and Sy-CID and were consistent signs in patients with HIGE and Wiskott–Aldrich syndrome (WAS) and DOCK8 deficiency." (PMID 34659256, 2021).
Autoimmunity (19 papers, 2018 to 2026). The occurrence of an immune reaction against the organism's own cells or tissues. "Furthermore, BCR repertoire demonstrated high diversity without clonal expansions, portraying an abnormal B-cell development leading to a possible mechanism for atopy and autoimmunity, alongside inadequate activation in DOCK8 deficiency." (PMID 42090074, 2026). "Mutations in the gene encoding DOCK8 account for the majority of patients with AR-HIES2, referred to as DOCK8 deficiency, characterized by eosinophilia, elevated immunoglobulin E (IgE) levels, recurrent infections, atopic dermatitis (AD), allergies, autoimmunity and malignancy." (PMID 39044832, 2024). "Hypotheses explaining the susceptibility of DOCK8-deficient patients towards autoimmunity included defective Treg function." (PMID 30120291, 2018). "Thus, we focused on differences in signaling pathways driven by DOCK8 and revealed changes in integrin signaling, which were associated with autoimmunity." (PMID 30120291, 2018). "Dedicator of cytokinesis 8 deficiency is known to have a broad effect on the immune system resulting in combined immunodeficiency (CID), autoimmunity, and atopy with a striking resemblance to severe atopic disease." (PMID 35386989, 2021). "DOCK8 deficiency shares with IPEX some features such as atopic dermatitis, autoimmunity, recurrent infections including muco-cutaneous candidiasis but, with few exceptions, not inflammatory bowel disease." (PMID 30443250, 2018). "Our results of DOCK8 decrease affecting different lymphocyte subsets in autoimmune cases, indicates that the presence of autoimmunity is not limited to selective impairment of DOCK8 functions in Tregs." (PMID 30120291, 2018). "Since our findings pointed to a crucial role of DOCK8 in autoimmune diseases, we were interested in the potential functional changes of lymphocytes in autoimmunity, driven by DOCK8." (PMID 30120291, 2018). "There is a lack of definite evidence on whether mixed chimerism in DOCK8-deficient patients increases the risk of posttransplant autoimmunity." (PMID 37779528, 2023).
combined immunodeficiency (19 papers, 2012 to 2025). A broad classification of inherited disorders presenting at birth that affect both the cell-mediated and humoral aspects of the immune response. "Dedicator of cytokinesis 8 (DOCK8) deficiency is a combined immunodeficiency (CID) due to biallelic mutations in the gene encoding DOCK8." (PMID 39936153, 2024). "DOCK8 deficiency is a rare IEIs seen predominantly in consanguineous populations, now recognized as a distinct form of combined immunodeficiency." (PMID 39044832, 2024). "Defects in the DOCK8 gene causes combined immunodeficiency termed DOCK8 immunodeficiency syndrome (DIDS)." (PMID 35373187, 2022). "For example, a novel GEF, dedicator of cytokinesis 8 (DOCK8) was recently identified as a regulator of immune cell function and mutations in DOCK8 have been detected in patients with severe combined immunodeficiency." (PMID 22461835, 2012). "Based on the update of IUIS phenotypical classification in 2022, AR DOCK8 deficiency was reclassified as a B cell low subgroup of combined immunodeficiency (CID)." (PMID 40040707, 2025). "Loss of function in DOCK8 may induce severe combined immunodeficiency in humans." (PMID 37188749, 2023). "The PIDs included the following: common variable immunodeficiency, severe combined immunodeficiency, DOCK8 deficiency, ataxia telangiectasia, CARD11 deficiency, MALT1 deficiency, chronic granulomatous disease, and a combined cellular and humoral immunodeficiency syndrome of unknown etiology." (PMID 36950172, 2023). "Lack of DOCK8, due to DOCK8 gene mutation, results in a type of combined immunodeficiency that presents with a diverse range of clinical symptoms." (PMID 39616183, 2024). "On one hand, an impaired formation of the immune synapse reflects on reduced cooperation between immune cells and defective lymphocyte activation and cytotoxic function, leading to more or less severe combined immunodeficiency, as in DOCK2, DOCK8, Coronin 1, and WIP deficiencies." (PMID 33809703, 2021). "Such diseases include CD25 or IL-2RA deficiency, mutations within STAT5b, STAT1 or STAT3, Dedicator of Cytokinesis 8 (DOCK8) deficiency as well as infantile or eosinophilic enteropathies and severe combined immunodeficiency (SCID)." (PMID 35207219, 2022). "PIDs with HPV clinical implications include epidermodysplasia verruciformis (EV), WHIM (warts, hypogammaglobulinemia, infections and myelokathexis) syndrome, DOCK8 mutations, GATA binding protein 2 (GATA2) mutations, and severe combined immunodeficiency (SCID)." (PMID 36960048, 2023).